IFNG (interferon gamma)
Diseases named in the same sentence as IFNG in open-access papers (continued):
Sharing a sentence is not in itself a finding about the gene and the disease.
breast cancer (647 papers, 1989 to 2026). A primary or metastatic malignant neoplasm involving the breast. "Consistently, F3 exhibited high similarity to several iCAF-associated signatures, including PCa iCAF, detox iCAF and IFNg iCAF from breast cancer." (PMID 41378308, 2025). "Our study investigated the effects and underlying mechanisms of OTUB1 on the breast cancer cell cycle and proliferation in IFNγ stimulation." (PMID 38664499, 2024). "Our analyses suggest that CD86-CD70 and CD274-CD70 immunoregulatory interactions are significantly associated with IFNγ expression in uterine corpus endometrial carcinoma and basal-like breast cancer, respectively." (PMID 37106127, 2023). "We developed a replication-deficient Semliki Forest virus vector expressing IFNg (SFV/IFNg) and evaluated its immunomodulatory antitumor potential in vitro in a model of 3D spheroids and in vivo in an immunocompetent 4T1 mouse breast cancer model." (PMID 34835178, 2021). "Among breast cancer patients, differential responsiveness of monocytes to IFNγ+GM-CSF stimulation was associated with distinct gene expression profiles, including differential expression of genes linked to the IFN response." (PMID 33042791, 2020). "In an effort to identify the factors that caused the facilitating effect, we incubated breast cancer cell with IFNγ that is secreted almost exclusively by T cells." (PMID 29350274, 2018). "Low expression of IFNGR1 leads to a functional blockade of IFNγ signaling and is associated with breast cancer.Antigen-specific inflammation in cows' mammary gland is characterized by overexpression of interleukins and IFN-γ." (PMID 30271395, 2018). "STAT1 deficiency ablates IFNγ-stimulated PD-L1 levels in MT/ShcA+/+ and MT/Shc313F/313F breast cancer cells." (PMID 28276425, 2017). "Correspondingly, a single STAT responsive element has been identified within the MUC1 promoter, that when mutated both decreases MUC1 promoter activity in breast cancer cells and also abolishes stimulation by interleukin-6 and interferon-gamma." (PMID 27768738, 2016). "Decreased peripheral abundance of γδTCR+ T cells and their diminished IFNγ production were recently shown to be associated with breast cancer." (PMID 21846333, 2011). "We observed similar patterns of association in Set2, and in particular while IL12, IL2 and IFNG were associated with good prognosis in ER- breast cancer, IL13 correlated with poor outcome." (PMID 21050467, 2010). "While these findings may seem contradictory to previous experimental results, they suggest that TPST2 is associated with tumor immunity including IFNγ signaling, and cell cycle regulation in breast cancer tissues." (PMID 39095793, 2024). "The relationship between somatic mutations and the IFNγ+ signature shows a moderate correlation (Spearman’s ρ = 0.33), indicating that the immune response in breast cancer may in part be driven by somatic mutation derived neoantigens." (PMID 39149486, 2024). "Importantly, the IFNγ signature had a strong prognostic significance in a TCGA cohort of breast cancer patients associated with high IFNγ signature positivity correlating with superior survival." (PMID 35902886, 2022). "To evaluate whether altered expression of the IL‐18 gene have an effect on YAP1, associated with breast cancer progression and metastasis, we studied the expression of IL‐18, IFNG and YAP1 genes." (PMID 34196131, 2022). "Thus, oxidative stress underlies the synergistic effects of phenformin and IFNγ-driven STAT1 activation in potentiating breast cancer cell death." (PMID 34083537, 2021). "The rs4648090 polymorphism has also been related to decreased risk of breast cancer among women with European ancestry and to interact with other SNPs in the IFNG, IRF2, IL6, and NFKB1 genes to affect risk of colon cancer, and with IRF6 and NFKB1 genes for risk of rectal cancer." (PMID 30781516, 2019).
breast cancer (continued). "Based on the evidence that the T allele is associated with a higher level of IFNG than the C allele the association of this SNP with this type of cancer is predictable, given that at breast cancer diagnosis, inflammatory cytokines are detected at elevated levels." (PMID 27220278, 2016). "In this study, fermented mung bean treatments in vivo were studied by monitoring tumor development, spleen immunity, serum cytokine (interleukin 2 and interferon gamma) levels, and spleen/tumor antioxidant levels after injection with low and high risk 4T1 breast cancer cells." (PMID 23710232, 2013). "Here, we show that induced Treg depletion in mice selectively unleashes IFNγ-producing γδ T cells, which are required for tumor control in an orthotopic breast cancer model." (PMID 42126428, 2026). "Transferring clinical phenotypes across cancer types provides an alternative approach to breast cancer prognosis, reflecting tumor homogeneity through interferon gamma-related processes." (PMID 39788975, 2025). "The present study investigated IFNγ levels (as a surrogate marker for NKA) in patients undergoing neoadjuvant treatment for breast cancer." (PMID 41226397, 2025). "For example, interferon gamma (IFNγ) released by T cells has been reported to increase cancer stemness in breast cancer via nuclear factor kappa-B (NF-κB)/LAT1 pathway, and co-inhibition of LAT1 and BCAT1 reduced this effect." (PMID 41502503, 2025). "Natural killer (NK) cells play a crucial role in maintaining the dormant state of breast cancer cells through the production of interferon-gamma (IFN-γ)." (PMID 41219968, 2025). "As Icosl depleted, breast cancer didn’t release sIcosl and also significantly enhanced IFNγ expression and inhibited LAG3 presence in both CD4+ and CD8+ T cells." (PMID 40708008, 2025). "Four daily doses of anti-TAG72-IL-2 monotherapy for TAG-72-expressing orthotopic murine mammary tumors in immunocompetent mice resulted in minimal whole-body toxicity and significant tumor growth reduction mediated by tumor infiltration of IFNγ+ CD8+ T cells." (PMID 40361381, 2025). "Similar upregulation of immune response signals was observed when comparing between molecular subtypes, with higher inflammatory and interferon gamma response signals observed in Basal-like breast cancer patients." (PMID 40671797, 2025). "Murine mammary cancer cells were infected with SFV delivering tumour necrosis factor-α (TNFα) or interferon-γ (IFNγ) genes." (PMID 40547518, 2025). "Earlier studies indicate that in a model of prolonged bacterial infection and in a model of mouse mammary carcinomas iron has strong and highly specific effects on IFNγ producing T cells." (PMID 40939292, 2025). "Linalool improves Th1 cellular immunity in breast cancer cells by inducing the release of IFNG and TNF in lymphocytes." (PMID 39759512, 2024). "The only member of the type II interferon family that is very unique is the Interferon-Gamma (IFNγ) that have shown autocrine signaling in breast cancer cells through a dependent gene signature that can cause cell cycle arrest and apoptosis." (PMID 39765744, 2024). "Our data demonstrated that TPST2 knockdown enhanced IFNγ signaling in human breast cancer cell lines (MDA-MB-231 and MDA-MB-468) and mouse breast (4T1 and colon (MC38) cancer cell lines." (PMID 39095793, 2024). "Interferon gamma plays context-dependent dual tumor-suppressor and pro-tumorigenic roles in breast cancer." (PMID 38579257, 2024). "Collectively, these findings indicate that TPST2 exerts inhibitory effects on IFNγ signaling in breast cancer cells." (PMID 39095793, 2024). "The inhibitory role of TPST2 in IFNγ signaling was verified in another breast cancer cell line, MDA-MB-486." (PMID 39095793, 2024). "We have employed a newly developed combinatorial search algorithm to detect protein post-translational modifications in a collection of breast cancer cell lines stimulated with interferon gamma." (PMID 39337390, 2024).
breast cancer (continued). "Engineered NK cells were co-cultured with PDL1+ breast cancer cells to evaluate their cytotoxic activity and ability to produce interleukin-12 (IL-12) and interferon-gamma (IFNγ) upon interaction with the target cells." (PMID 38666913, 2024). "The expression levels of PLK1 and IFNG in breast cancer tissues were significantly higher than those in the paired adjacent normal tissues." (PMID 39314848, 2024). "A similar study in breast cancer showed that PBMC-derived macrophages treated with cancer cell conditioned media and cisplatin had increased IFNγ, IL6, and TNFα signaling, pathways typically associated with M1-like phenotypes." (PMID 39287565, 2024). "Gene expression analysis from in vitro mammosphere formation revealed IFNG, CXCR5, CD40LG, TBX21, and IL2RG to be associated with the CSC phenotype and also displayed prognostic value for patients with breast cancer." (PMID 39001456, 2024). "Here, we apply a novel combinatorial algorithm to search for modifications in a collection of data files obtained from experiments in which we stimulated breast cancer cell lines with the cytokine interferon gamma." (PMID 39337390, 2024). "For example, the ability of IFNγ-induced IRF1 to participate in several antitumor mechanisms has been demonstrated in breast cancer cells." (PMID 38396830, 2024). "The effect of Tpst2 down-regulation on IFNγ responsiveness was also observed in mouse breast cancer 4T1 cells." (PMID 39095793, 2024). "Gene expression analysis revealed IFNG, CXCR5, CD40LG, TBX21 and IL2RG to be associated with the CSC phenotype and also displayed prognostic value for patients with breast cancer." (PMID 38831317, 2024). "In breast cancer tissue samples from TCGA, the expression of TPST2 is significantly associated with increased expressions of IFNγ signaling-related genes." (PMID 39095793, 2024). "Applications in uterine corpus endometrial carcinoma and basal-like breast cancers (TNBC) nominated tumor-immune interactions, that co-associate with interferon gamma (IFNγ), the key cytokine and effector of antitumor immunity." (PMID 37106127, 2023). "In aggregate, our RNA-seq and ATAC-seq data indicate that ER+ breast cancer cells are poised for an enhanced response to IFNγ after ER blockade, and IFNγ stimulation leads to an enhanced downstream response in HD conditions." (PMID 37450351, 2023). "Future research needs to explore the mechanism of IFNG in the breast cancer tumor microenvironment and actively promote the clinical application." (PMID 37154982, 2023). "Further analysis indicated that IFNG expression in tumor tissues was positively correlated with the degree of CD8+ T cell infiltration in breast cancer." (PMID 37154982, 2023). "In this regard, a previous study on breast cancer reported that IFNγ, through its downstream effector IRF1, is capable of inducing the global AS perturbation of genes involved in the regulation of growth and differentiation, as well as cytokine genes." (PMID 38067106, 2023). "Women with breast cancer improved stimulated TNFα and IFNγ following a 16 week exercise intervention, which suggests that training status influences this response." (PMID 37325799, 2023). "Immunohistochemistry was used to verify the expression of the signature gene IFNG in breast cancer samples and we further explored the relationship between IFNG and immune infiltrating cells in the breast cancer tumor microenvironment." (PMID 37154982, 2023). "Our results suggested that IFNG was the most promising predictor we found and was most closely related to immunotherapy in breast cancer patients." (PMID 37154982, 2023). "The relationship between the signature gene IFNG and breast cancer tumor microenvironment was analyzed." (PMID 37154982, 2023). "The expression of IFNG was positively correlated with CD8+ T cell infiltration in the breast cancer tumor microenvironment." (PMID 37154982, 2023).
breast cancer (continued). "IFNG is a driver of the association between NK cells and clinical response to trastuzumab in patients with HER2-positive breast cancer." (PMID 37154982, 2023). "In highly metastatic breast cancer cell lines, an analogous subset is described demonstrating delayed class II upregulation following IFNγ exposure, mediated by IFNγ-induced EZH2 occupancy at CIITA." (PMID 37565053, 2023). "Our study constructed the prognostic signature based on breast cancer PD-1/PD-L1 pathway molecular typing-related genes (IFNG, JCHAIN, ELOVL2, PIGR, PAGE5, ACTL8, and CLEC3A)." (PMID 37154982, 2023). "Cell changes in these responding breast cancer patients were accompanied by a sustained increase in IFNγ, a trend that was also observed in the responding patient here." (PMID 36208017, 2023). "We showed that after ER blockade, ER+ breast cancer cells are poised for an enhanced response to IFNγ through NF-κB signaling." (PMID 37450351, 2023). "Previous studies have shown that CEACAM1 possesses an ISRE in its promoter region and is synergistically induced by TNFα and IFNγ in endothelial cells, colorectal carcinoma cells, cervix carcinoma cells, and breast carcinoma cells." (PMID 37691945, 2023). "This work aimed to determine and characterize IFNG and co-expressed genes, and to define their implications in breast carcinoma (BRCA)." (PMID 37408777, 2023). "Inflammatory CD4+ T cells drive breast cancer cells into senescence by releasing interferon-gamma and tumor necrosis factor-alpha, which directly bind to their receptors on cancer cells." (PMID 36467403, 2022). "As expected, IL‐18 induced IFNG gene alteration has been increased dramatically in metastatic breast carcinoma, which denotes the failure of IL‐18 to stop genetic alteration of IFNG in advanced breast cancer." (PMID 34196131, 2022). "Trofimova, O.; Korotkaja, K.; Skrastina, D.; Jansons, J.; Spunde, K.; Isaguliants, M.; Zajakina, A. Alphavirus-Driven Interferon Gamma (IFNg) Expression Inhibits Tumor Growth in Orthotopic 4T1 Breast Cancer Model." (PMID 35804458, 2022). "Similar to our observations, trastuzumab (anti-HER2 antibody) was shown to upregulate PD-L1 level in HER2-overexpressing human breast cancer cells by stimulating human peripheral blood mononuclear cells to release IFNγ." (PMID 35078921, 2022). "Although predominantly expressed by professional antigen-presenting cells, MHC-II can be induced in breast cancer cells by IFNγ released by activated T cells into the microenvironment." (PMID 35351903, 2022). "In a model of breast cancer, elevated MIF expression supported tumor growth while a loss of MIF promoted the anti-tumor immune infiltration of CD4+/CD8+ T cells producing IFNγ, which supported the MIF immunosuppressive function." (PMID 36496973, 2022). "Using NK cells from patients with breast cancer, Slattery and colleagues showed that these cells had reduced IFNγ production, cytotoxicity, and reduced rates of OxPhos and glycolysis compared to healthy NK cells." (PMID 36498937, 2022). "Whereas in primary breast cancer, the genetic alteration of IFNG is significantly low and IL‐18 and YAP1 showed almost same level of gene alteration." (PMID 34196131, 2022). "Using the mouse 4T1 orthotopic breast cancer model, a striking drop in IFNγ+ T cells was detected in both spleen and lungs of tumor-bearing mice, which suggested tumor-elicited systemic immunosuppression." (PMID 35126389, 2022). "Herein, we integrated transcriptomic and epigenomic profiling to characterize the acute epigenetic changes induced by IFNγ stimulation in a murine breast cancer model." (PMID 35902886, 2022). "Prior to IFNγ stimulation, the TFs demonstrating the highest connectivity were dominated by TFs previously identified for regulating facets of breast cancer biology (in black), including SOX9, GATA3, and ETV6." (PMID 35902886, 2022).
breast cancer (continued). "On the other hand, α-tocopheryl succinate, the most effective form of vitamin E, which holds great anticancer potential, was delivered by NPTs (NP-TOS15) to 4T1 breast cancer cells, in combination with interferon-gamma (IFN-γ)." (PMID 33572626, 2021). "We show that MitoTEMPO, a mitochondrial ROS scavenger, reversed the cytotoxic effects of IFNγ/phenformin combination treatment in three independent breast cancer models (MT4788, MDA-MB-231, and BT474)." (PMID 34083537, 2021). "In support of this, IFNγ treatment leads to a modest but statistically significant increase in breast cancer viability in response to reduced glutamine levels." (PMID 34083537, 2021). "In the current study, we characterized the ability of the SFV/IFNg vector to activate BMDMs towards the M1 phenotype and evaluated its effect on 4T1 mouse breast cancer cells in a three-dimensional (3D) spheroid model in vitro." (PMID 34835178, 2021). "In this study, we examined five cancer immunity-related pathways (IFNα, IFNγ, STAT3, TGFβ and TNFα) in four large independent breast cancer cohorts (n = 6,381) and their associations with the prognosis of breast cancer subtypes." (PMID 33767579, 2021). "Using these STAT1-null cells, we found that STAT1 is required for IFNγ to sensitize breast cancer cells to the antitumorigenic effects of phenformin." (PMID 34083537, 2021). "Consistently, IFNγ-driven STAT1 activation led to a 30% reduction in the bioenergetic capacity of breast cancer cells compared to the 25-fold reduction observed with phenformin treatment, either alone or combined with IFNγ." (PMID 34083537, 2021). "While interesting, these observations cannot explain the increased synergy observed with IFNγ and phenformin in stimulating cytotoxic responses in breast cancer cells." (PMID 34083537, 2021). "In this study, we have shown that the SFV/IFNg vector inhibits tumor growth in an orthotopic 4T1 mouse breast cancer model." (PMID 34835178, 2021). "IFNγ-secreting TA-reactive Teff are enriched in breast cancer patients, exhibit potent tumor-killing properties, and possess therapeutic potential." (PMID 33602930, 2021). "To address this, we performed genome-wide RNA-sequencing (RNA-seq) analysis on control and STAT1-deficient breast cancer cells (MT864 and MT4788) following IFNγ stimulation." (PMID 34083537, 2021). "IFNγ-induced STAT1 activation cooperates with phenformin to reduce the viability of MT breast cancer cells." (PMID 34083537, 2021). "In a cohort of early stage breast cancer, patients who relapsed had dysregulated IFNγ-signalling in monocytes at time of diagnosis." (PMID 34557196, 2021). "Among the mutated proteins, 10 reference genes were associated with breast cancer DMFS or OS and were involved in the response to interferon gamma." (PMID 35096604, 2021). "Breast cancer patients harbor in PB IFNγ-producing CD4+Teff but also suppressive CD4+Treg reactive to MAMI33,35,36." (PMID 33602930, 2021). "In breast cancer, it was reported that the expression of PD-L1 was mainly regulated by IFNγ via the JAK/STAT pathway." (PMID 34365463, 2021). "In this study, we have evaluated the therapeutic potential of the SFV/IFNg vector in a three-dimensional (3D) in vitro system and in a mouse breast cancer model in vivo." (PMID 34835178, 2021). "IFNγ treatment modestly reduced the basal and maximal respiration rates of breast cancer cells and in a STAT1-dependent manner." (PMID 34083537, 2021). "Previous studies described anti-tumor CD8(+) T cell responses with increase in IFNγ levels in pCR Her2-positive breast cancer patients undergoing neoadjuvant chemotherapy." (PMID 32306920, 2020). "The inducible overexpression of PTPN2 not only repressed IFNγ‐induced p‐STAT‐1 and Cxcl9/10 expression, but most importantly also the recruitment of PTPN2‐deficient CAR T cells to HER‐2‐E0771 mammary tumours in vivo." (PMID 31803974, 2020).